RN7SKP33 (RN7SK pseudogene 33)
Gene: Miscellaneous RNA gene on chromosome 20 (46,859,333 to 46,859,672, forward strand). Ensembl gene ENSG00000222874.
Homologues: Orthologues: chimpanzee 7SK (99% identical), mouse Gm54885 (56% identical), mouse Gm55949 (52% identical), mouse Gm54941 (19% identical). Paralogues in human: RN7SKP203 (71% identical), RN7SKP90 (70% identical), RN7SKP217 (69% identical), RN7SKP162 (69% identical), RN7SKP133 (68% identical), RN7SKP240 (68% identical), RN7SKP255 (68% identical), 7SK (67% identical), RN7SKP224 (67% identical), RN7SKP176 (67% identical), RN7SKP189 (67% identical), RN7SKP281 (67% identical), and 284 more.